MIF (macrophage migration inhibitory factor)
Diseases named in the same sentence as MIF in open-access papers (continued):
Sharing a sentence is not in itself a finding about the gene and the disease.
tumor (continued). "Several studies investigating potential roles for MIF in DC-dependent anti-tumor immunity suggest that MIF functionally impairs the ability of DCs to present TAAs to T cells leading to a dampening of anti-tumor responses." (PMID 33324425, 2020). "MIF, which is secreted by tumor-specific T-cells, is reported to be especially involved in the pre-metastatic niche during the process of bone metastasis by means of intravasation, angiogenesis and EMT in breast cancer circulating tumor cells (CTCs)." (PMID 32674405, 2020). "Macrophage Migration Inhibitory Factor (MIF), a pleotropic cytokine involved in multiple biological processes including tumor metastasis, is also implicated in MSC homing to tumors." (PMID 32133358, 2020). "Furthermore, the macrophage migration inhibitory factor (MIF), whose function as a regulator of inflammation remains controversial, seems to promote cancer progression by stimulating the recruitment of myeloid cells into the tumor, is also associated with increased angiogenesis." (PMID 31906296, 2020). "CCL2 produced by murine GBM cells recruits CCR4+Tregs and CCR2+Ly-6C+ mMDSCs while MIF produced by tumor stem cells activates MDSCs, resulting in an immunosuppressive tumor microenvironment." (PMID 32707672, 2020). "Given that DCs cross-present antigens to CD8+ T cells via MHC-I, this finding indicates that MIF promotes immunosuppression, in part, by dampening DC cross-presentation of tumor antigens." (PMID 33324425, 2020). "In several types of cancers, MIF can promote tumor growth by multiple strategies, including promoting angiogenesis via upregulating the secretion of VEGF 45-48." (PMID 32550907, 2020). "Like SDF-1, tumor-secreted MIF binds, among other receptors, to CXCR4 (Gi-protein coupled receptor) and activates MAP kinase signaling pathway, eventually inducing MSC migration through upregulating cell motility genes." (PMID 32133358, 2020). "The critical biological activities required for tumor initiation and progression, including angiogenesis, cell proliferation, and apoptosis, are regulated by MIF." (PMID 32943608, 2020). "After iNPR-A treatment, the tumor burden and expression of macrophage migration inhibitory factor (MIF) in mice were reduced." (PMID 33335885, 2020). "Intraperitoneal treatment with ISO-1 markedly attenuated tumour growth, with significant reduction in tumour volume and weight, and downregulation of MIF expression in ISO-1 treated tumour tissues." (PMID 32317702, 2020). "We have shown that, among these secreted factors, MIF will have an important pro-tumorigenic role, as it had an autocrine tumor-promoting effect by inducing cell survival and a paracrine effect in neighboring cells by inducing tumor cell migration." (PMID 31963754, 2020). "To examine the role of MIF in promoting tumor growth and metastasis, we used MIF expressing (scr) and MIF depleted (MIFsh1) MDA-MB-231 cells in vivo." (PMID 32943608, 2020). "MIF is upregulated in NB tumor tissues and cell lines and it contributes to NB aggressiveness and immune-escape." (PMID 32155795, 2020). "An important consideration not discussed in this review is the respective role and contributions of the MIF ortholog, MIF-2, in tumor immunity." (PMID 33324425, 2020). "Orthotopic implantation of TNBC cells into MIF knockout mice showed reduced tumor growth compared to wild-type mice." (PMID 32943608, 2020). "At the site of the primary tumor, macrophage migration inhibitory factor (MIF) can induce EMT and tumorigenicity in many cancer types." (PMID 32182935, 2020). "Taken together, these data reveal that CD74/MIF inhibition via Ibudilast can reduce MDSCs in vivo and increase immune activation in the tumor microenvironment." (PMID 32625208, 2020). "Here we have shown that in TNBC patients, MIF expression was significantly enriched in the tumor compared to adjacent normal tissue." (PMID 32943608, 2020).
tumor (continued). "The targeting of MIF indeed conferred a survival advantage to tumor-bearing mice and increased the cytotoxic T cells within the tumors." (PMID 33374253, 2020). "MIF has been shown to increase angiogenesis and dampen antitumor immune surveillance to support tumor cells to acquire metastatic properties." (PMID 32943608, 2020). "This review will summarize the studies describing MIF in tumor-specific innate and adaptive immune responses and attempt to reconcile these various pleiotropic functions in normal physiology." (PMID 33324425, 2020). "Our results are in agreement with a recent study showing that MIF directs mesenchymal stem cell migration and infiltration toward tumor cells." (PMID 32318567, 2020). "Using an orthotopic mouse model of MIF KO, we observed a significantly reduced tumor growth in MIF KO mice compared to wild-type (WT) mice emphasizing the indispensability of host secreted MIF for tumor growth and progression." (PMID 32943608, 2020). "Many of these complexes are under populated by HLA-DRs, leaving CD74 molecules on the surface of the cell that can bind to MIF and function as a transcription factor to promote tumor cell survival." (PMID 32934776, 2020). "Intracellular MIF was found to be overexpressed in tumor tissues of NB patients and significantly correlated with the grade of tumor differentiation and N-Myc expression." (PMID 32155795, 2020). "Similar to its role in other cancers, we strongly emphasize the role of MIF in promoting tumor growth and metastasis in TNBC." (PMID 32943608, 2020). "MIF’s functions in eliciting either pro- or anti-tumor immune responses in individual effector cell types are numerous and often context-dependent." (PMID 33324425, 2020). "In conclusion, these findings establish an important role of MIF in tumor growth, progression, and metastasis of TNBC cells." (PMID 32943608, 2020). "MIF has been reported to enhance the aggressiveness of tumor cells by augmenting the angiogenic potential of various human cancers." (PMID 32943608, 2020). "Other studies identifying a contributory role for MIF in MDSC-dependent tumor progression include a finding that an IG-CDR-based peptide that disrupts MIF-CD74 signaling is sufficient to reduce M-MDSC accumulation in metastatic melanoma lesions." (PMID 33324425, 2020). "Macrophages also express the macrophage migration inhibitory factor (MIF), which contributes to immune escape and tumor progression." (PMID 33244317, 2020). "CRC cells have been reported to secrete MIF at concentrations sufficient to attract T lymphocytes to the tumor, and MIF can drive macrophage, neutrophil, and T cell migration in a chemokine-like manner." (PMID 31360118, 2019). "MIF as a proinflammatory cytokine was determined to be upregulated in all stages of neoplasia in most types of cancers and metastatic conditions." (PMID 31877723, 2019). "Reduction of MIF conferred a survival advantage to tumor-bearing animals and increased the cytotoxic T cell response towards the tumor." (PMID 31225500, 2019). "Several reports have shown that miR-451a suppresses proliferation, migration and promotes the apoptosis of tumor cell by targeting MIF." (PMID 31608058, 2019). "The present study shows a different perspective on the role of MIF in modeling the tumor microenvironment." (PMID 31360118, 2019). "The pro-inflamatory cytokine MIF (Macrophage migration inhibitory factor) is overexpressed in various tumors, where it promotes tumor growth by the stimulation of multiple signaling cascades, including the AKT pathway." (PMID 31312183, 2019). "All these data support the idea that MIF influences the initial response against tumor cells, modulating early immune responses." (PMID 31360118, 2019).
tumor (continued). "All these effects pointed to a protective effect of Rb9 in face of the immune suppressive and tumor promoting activities of MIF." (PMID 32010152, 2019). "Numerous studies have shown that impeding MIF expression levels with antibodies or short interfering RNAs lead to significantly reduced tumor formation in vivo." (PMID 30814573, 2019). "It has also been proved that UM cells are capable of producing the macrophage migration inhibitory factor (MIF), a cytokine that inhibits cytolytic activity of NK cells, contributing to tumor growth and metastatic spread." (PMID 31357439, 2019). "Consistently, the immunohistochemical analysis of the tumor samples, the dasatinib and cisplatin combination group demonstrated the lowest staining intensity of Src, MIF, and CD155." (PMID 31036057, 2019). "CRC cell lines transplanted in mice are major MIF producers, or in the case of MIF inhibition, the genesis of the tumor prior to inhibition is supported by MIF." (PMID 31360118, 2019). "LPA-induced macrophage migration inhibitory factor (MIF) promotes both tumor cell growth and angiogenesis via both the Ras/MAPK and Ras–Akt/PI3K signaling pathways." (PMID 31658655, 2019). "We demonstrated that MIF participates in the recruitment of macrophages to the tumor site in the murine CRC model." (PMID 31360118, 2019). "Ren and colleagues have shown that inhibition of MIF expression, via antisense cDNA, in NB cells determined a significant reduction in tumor growth in vitro and tumor metastasis in vivo." (PMID 31635049, 2019). "Increasing evidence is emerging on the pivotal role of MIF multiple functions in the onset and maintenance of carcinogenesis in various neoplastic diseases, including lung, bladder and breast cancer." (PMID 31557914, 2019). "As described in detail previously with regard to H. pylori and MIF, tumor microenvironment is an important concept in tumorigenesis." (PMID 30742638, 2019). "For example, macrophage migration inhibitory factor (MIF) overexpression has been reported in OC and correlates with tumor progression." (PMID 31456796, 2019). "Our immunohistochemical data are in line with those of previous studies that demonstrated MIF and CD74 expression by tumor-associated fibroblasts, leukocytes and endothelial cells." (PMID 31866994, 2019). "Evidence supports the role of MIF in tumorigenesis and tumor progression, especially in the background of tumor microenvironment." (PMID 30742638, 2019). "During progression of cancer, MIF has the ability to change tumor microenvironment favorable for tumor aggressiveness." (PMID 30981278, 2019). "Although MIF absence can explain the less-differentiated and more malignant tumors, it cannot be correlated to the increased proliferation of tumor cells in MIF−/− mice." (PMID 31360118, 2019). "We waited until the tumor was grown to a substantial size before commencing treatment in contrast to investigations using siRNA or shRNA to block MIF expression." (PMID 30814573, 2019). "All of these studies, when taken together, suggest that MIF is an important mediator of the immunosuppressive tumor microenvironment." (PMID 29864117, 2018). "To examine the role of MIF in tumor growth using this model, we compared female MIF-expressing (WT) and MIF-deficient (MIF KO) MMTV-PyMT transgenic mice." (PMID 29864117, 2018). "MIF KD tumors contained both a greater percentage of activated DCs, as well as a greater number per mg of tumor when compared to MIF expressing tumors." (PMID 29864117, 2018). "This suggests that MIF is an important mediator in establishment of an immunosuppressive tumor microenvironment." (PMID 29864117, 2018). "When comparing late-stage, age-matched 5-month-old mice, MIF KO mice had significantly less total tumor burden compared to WT mice, as well as fewer tumors at the largest end of the size distribution." (PMID 29864117, 2018).
tumor (continued). "The Macrophage Migration Inhibitory Factor (MIF) is an inflammatory cytokine that is overexpressed in a number of cancer types, with increased MIF expression often correlating with tumor aggressiveness and poor patient outcomes." (PMID 29864117, 2018). "Our results demonstrate that tumor cell-derived MIF is responsible for several aspects of the anti-tumor immune response in tumor-bearing animals." (PMID 29864117, 2018). "MIF KD tumors contained significantly more tumor-infiltrating CD8+ T cells, both as a percent of total CD3+ T cells and by absolute cell number." (PMID 29864117, 2018). "This time point was selected because it is the earliest time point at which a statistically significant difference in tumor size between WT and MIF KD tumors is detectable." (PMID 29864117, 2018). "This reflects previous reports demonstrating the production of MIF in presence of growth factors and inducing tumor growth." (PMID 30564558, 2018). "This is in agreement with the common observation that expression of MIF correlates with tumor aggressiveness in patients." (PMID 29864117, 2018). "Binding to CD74 mainly mediates survival and proliferative functions of MIF on immune and tumor cells." (PMID 29977203, 2018). "Together, these data suggest that loss of MIF expression in the MMTV-PyMT model leads to a delay in tumor appearance and reduction in tumor growth." (PMID 29864117, 2018). "Recently, several studies, including our own, strongly suggest that MIF exerts its pro-tumorigenic effects through modulation of the immunosuppressive tumor microenvironment." (PMID 29864117, 2018). "Nonetheless, this small difference suggests that there is some amount of T-cell mediated tumor growth control even in the setting of MIF–expressing tumors, but that this effect is very modest compared to the impact of T cells on the growth of MIF KD tumors." (PMID 29864117, 2018). "H-RS cells secrete Colony Stimulating Factor-1 (CSF-1) and macrophage migration inhibitory factor (MIF) to recruit M2 macrophages, which in turn, secrete chemokines like, IL-8, to attract neutrophils into and eotaxin to attract eosinophils into tumor tissue." (PMID 30101129, 2018). "Further dissection of the relative contribution of CD4 versus CD8 cells to the MIF-dependent immune-mediated control of tumor growth will be of interest in future studies." (PMID 29864117, 2018). "In this study, we aimed to better understand the link between primary tumor expression of MIF and increased tumor growth." (PMID 29864117, 2018). "To test this, we examined WT and MIF KD 4T1 tumor-bearing mice for the presence and activation status of tumor-infiltrating and lymph node DCs." (PMID 29864117, 2018). "Another in vitro study has shown that specific blockade of MIF in GBM cells reduced the growth rates of tumor cells, both under confluent and over-confluent conditions, thus anticipating a role of MIF in overcoming contact inhibition." (PMID 29707160, 2018). "Tumor tissue MIF expression and plasma levels correlated with tumor recurrence and metastasis, and overall survival." (PMID 29707160, 2018). "Based on these observations, we propose a model whereby MIF-deficient 4T1 cells undergo ICD, leading to an enhanced abundance and activation of DCs in the tumor microenvironment." (PMID 29864117, 2018).
tumor (continued). "We have previously demonstrated that depletion of MIF in the 4T1 model results in delayed tumor growth and impaired metastasis." (PMID 29864117, 2018). "The corollary of this model is that an evolving tumor can overcome the growth suppressing anti-tumor effects through mechanisms that increase MIF expression." (PMID 29864117, 2018). "Together, our data suggests a model in which MIF expression in the primary tumor dampens the anti-tumor immune response, promoting tumor growth." (PMID 29864117, 2018). "This dual and opposite effect of MIF on the immune response depends on the cytokine milieu in the tumor microenvironment and on the levels of MIF." (PMID 29875777, 2018). "MIF plays important roles in inflammation regulation, cell proliferation, angiogenesis, tumor formation, and can also participate in tumor regulation." (PMID 28753959, 2017). "We also examined cultured MTFs for expression of the pro-carcinogenic cytokine MIF, because of MIF’ s prominent roles in M2 polarization of macrophages, the tumor microenvironment (TME), and cancer progression." (PMID 28957348, 2017). "MIF targets also NKG2D expression by transcriptionally downregulating NKG2D in NK cells to diminish cytotoxicity toward tumor cells." (PMID 28275576, 2017). "Our results therefore suggest that the anti tumor effect predicted to be exerted by CD74's role in facilitating the immune response is dominant over the protumor effect involving MIF signal transduction, expected from laboratory studies on MIF." (PMID 27058619, 2017). "Extensive studies have emphasized the roles of MIF on the monocytes/macrophages, as well as various tumor cells." (PMID 27926507, 2017). "This study illustrated the tumor-suppressive role of miR-451 and validated MIF as a target of miR-451 in NSCLC from clinicopathological and cell biological points of view." (PMID 28704499, 2017). "The increased MIF expression of tumor cells promotes tumor growth through the activation of MAPK/PI3K/Akt pathways by the autocrine or paracrine loop." (PMID 28704499, 2017). "miR-451 is a tumor suppressive microRNA with several target genes, including Macrophage migration inhibitory factor (MIF)." (PMID 28704499, 2017). "Several lines of evidence indicate that MIF is a candidate target gene of miR-451 and promotes tumor progression." (PMID 28704499, 2017). "MIF is reported to be upregulated in virtually all stages of neoplasia in most types of cancers and metastatic conditions." (PMID 29247872, 2017). "MIF also accelerates tumor growth by activating the MAPK/PI3K/Akt pathways, promoting tumor-associated angiogenesis and inhibiting the antitumor immune response through the autocrine or paracrine mechanism." (PMID 28704499, 2017). "The activation of the PI3K/Akt pathway with its cell survival promoting effects by the MIF-CD74/CD44 axis is congruent with observations that various tumors express Ii/CD74 and MIF shows a tumor promoting effect in some systems." (PMID 28208600, 2017). "Recently, we have shown that the majority of the malignant mesothelial tumor cells expressed MIF and its receptor CD74, with a homogenous distribution between the different histotypes." (PMID 26883190, 2016). "In murine models of human colorectal adenoma and metastatic breast cancer, inhibition of MIF expression by genetic deletion or RNA interference decreased tumor progression and metastasis." (PMID 26883190, 2016). "In summary, in MPM cell lines, activated MIF/CD74 pathway has a pro-tumorigenic function by increasing tumor cell proliferation and protecting them from apoptosis." (PMID 26883190, 2016). "MIF is a pro-tumorigenic protein influencing tumor cells and tumor stroma through several mechanisms." (PMID 26741693, 2016). "Another study showed that macrophage migration inhibitory factor (MIF) also promoted tumor metastasis by increasing the prevalence of a highly immunosuppressive subpopulation of MDSCs within the tumor." (PMID 28053982, 2016).